DCTN3 (dynactin subunit 3)
Description:
Part of the dynactin complex that activates the molecular motor dynein for ultra-processive transport along microtubules (By similarity). Together with dynein may be involved in spindle assembly and cytokinesis.
Synonyms: DCTN22; DCTN-22
Tractability: PROTAC: ubiquitination databases record sites on it; its protein half-life has been measured.
Gene: Protein-coding gene on chromosome 9 (34,613,545 to 34,620,523, reverse strand). Ensembl gene ENSG00000137100.
Subcellular location: Cytoplasm; Cytoplasm, cytoskeleton, microtubule organizing center, centrosome; Chromosome, centromere, kinetochore; Cytoplasm, cytoskeleton, spindle; Cleavage furrow; Midbody
Subcellular location (Human Protein Atlas): Cytosol; Calyx; Mid piece; Nucleoli; Perinuclear theca; Principal piece
Pathways (Reactome):
Cell Cycle: AURKA Activation by TPX2; Loss of Nlp from mitotic centrosomes; Loss of proteins required for interphase microtubule organization from the centrosome; Recruitment of NuMA to mitotic centrosomes; Recruitment of mitotic centrosome proteins and complexes; Regulation of PLK1 Activity at G2/M Transition
Vesicle-mediated transport: COPI-independent Golgi-to-ER retrograde traffic; COPI-mediated anterograde transport
Cellular responses to stimuli: HSP90 chaperone cycle for steroid hormone receptors (SHR) in the presence of ligand
Immune System: MHC class II antigen presentation
Organelle biogenesis and maintenance: Anchoring of the basal body to the plasma membrane
Gene Ontology:
Molecular function: protein binding; structural molecule activity
Biological process: cytoskeleton-dependent cytokinesis; mitotic cell cycle
Cellular component: centrosome; cleavage furrow; cytoplasm; cytosol; dynactin complex; midbody; perinuclear region of cytoplasm; microtubule associated complex; spindle
Genetic constraint (gnomAD): Loss-of-function variants: 25 observed, 29.7 expected, observed/expected ratio (o/e) 0.84, 90% interval 0.61 to 1.18. The upper end of that interval is the gene's LOEUF score, 1.18, which puts it in group 5 of 6, group 1 being the genes least tolerant of losing a copy. Missense variants: 229 observed, 240.6 expected, observed/expected ratio (o/e) 0.95, 90% interval 0.85 to 1.06. Synonymous variants: 81 observed, 93.81 expected, observed/expected ratio (o/e) 0.86, 90% interval 0.72 to 1.04.
Homologues: Orthologues: macaque DCTN3 (98% identical), dog DCTN3 (95% identical), mouse Dctn3 (94% identical), rat Dctn3l1 (93% identical), guinea pig DCTN3 (92% identical), pig DCTN3 (81% identical), chimpanzee DCTN3 (77% identical), rabbit DCTN3 (68% identical), tropical clawed frog dctn3 (66% identical), zebrafish dctn3 (56% identical).
Diseases named in the same sentence as DCTN3 in open-access papers:
DCTN3 is named in the same sentence as 11 diseases in open-access papers, as found by Europe PMC text mining. Sharing a sentence is not in itself a finding about the gene and the disease. The quoted sentences say what the papers report.
breast carcinoma (3 papers, 2013 to 2024). "We found that genetically determined DCTN3 protein levels were inversely associated with the risk of breast cancer." (PMID 39468330, 2024). "Increased protein expression levels were associated with a decreased risk of breast cancer for DCTN3 and DDX6, with p values of 1.01 × 10–3 and 3.25 × 10–4, respectively." (PMID 39468330, 2024). "DCTN3 has been associated with progression and metastasis formation in breast cancer." (PMID 25060540, 2014). "Among these five proteins, the corresponding genes for proteins COPG1, DCTN3, and DDX6 were located at least 1 Megabase away from the GWAS-identified breast cancer risk variants." (PMID 39468330, 2024). "In this first breast-tissue-based PWAS of breast cancer risk, we found that five proteins (COPG1, DCTN3, LSP1, DDX6, and DNAJA3) were significantly associated with overall breast cancer risk." (PMID 39468330, 2024). "Both DCTN3 and DDX6 were associated with a decreased risk of breast cancer with p values of 1.01 × 10–3 and 3.25 × 10–4, respectively." (PMID 39468330, 2024). "Among these five proteins, the corresponding genes for three proteins, including COPG1, DCTN3, and DDX6, were located at least 1Mb away from the GWAS-identified breast cancer risk variants." (PMID 39468330, 2024). "Previous research indicates that DCTN3 overexpression may play a role in breast cancer progression." (PMID 39468330, 2024).
lymph node metastasis (2 papers, 2013 to 2017). "This current study also revealed that amplification of 9p was significantly associated with lymph node metastasis that might be driven by proto-oncogenes such as CA9, VCP, DCTN3, and STOML2." (PMID 28384287, 2017).
prostate carcinoma (2 papers, 2007 to 2014). A carcinoma that arises from epithelial cells of the prostate gland. "This BAC clone contained two genes, IL-11RA and DCTN3, which were already thought to play a role in prostate cancer growth." (PMID 17712417, 2007). "We, therefore, screened 20 primary prostate cancer samples and found 75% of the tumors harboring an IL-11RA copy number gain alone, none of DCTN3 alone, and 10% of both genes." (PMID 17712417, 2007).
dysplasia (1 paper, 2014). A usually neoplastic transformation of the cell, associated with altered architectural tissue patterns. "Furthermore, lentiviral-mediated overexpression of VCP, DCTN3, and STOML2 in Cal-27 and POE9n-tert, OSCC and dysplasia cell lines with neutral DNA copy number at 9p13, enhanced both proliferation and anchorage independent growth." (PMID 25060540, 2014). "Furthermore, our results suggest that activation of candidate oncogenes is likely to be governed by additional events rather than a single DNA copy number gain event at 9p13: we detected DCTN3 overexpression in dysplasia tissue in the absence of increased gene dosage." (PMID 25060540, 2014).
leukemia (1 paper, 2013). A malignant (clonal) hematologic disorder, involving hematopoietic stem cells and characterized by the presence of primitive or atypical myeloid or lymphoid cells in the bone marrow and the blood. "Indeed, a study in a leukemia mouse model showed that the axonemal dynein light chain 4 (Dnalc4) and dynactin 3 (Dctn3) cooperate with NUP98-HOXA9 in mediating leukemogenesis." (PMID 23840580, 2013).
neuropathy (1 paper, 2022). A disorder affecting the nervous system that manifests with pain, tingling, numbness, and/or muscle weakness. "These evidence suggests that in addition to mitochondrial dysfunction, disruption of retrograde axon transport induced by Dctn3 reduction might be another possible pathogenesis of Fars2-related neuropathy." (PMID 35794642, 2022).
oral cancer (1 paper, 2014). "The functional significance of VCP, STOML2, and DCTN3 in oral cancer phenotypes was evaluated by shRNA-mediated knockdown experiments using oral cancer cell line SCC-9." (PMID 25060540, 2014). "Within this region, VCP, STOML2, and DCTN3 were identified as candidate oncogenes and we demonstrate that each is able to regulate oral cancer phenotypes." (PMID 25060540, 2014). "Of these four lines, only the amplicon in SCC-9 spanned all four oral cancer candidate genes defined by our analyses of oral cancer tissues (VCP, STOML2, and DCTN3)." (PMID 25060540, 2014).
tumor (5 papers, 2014 to 2024). "CDC20B, DCTN3, CEP295 and TIMLESS were shown to promote cell cycle progression and be associated with tumor progression in many types of cancer." (PMID 39527598, 2024). "Our study found seven downstream factors that may be associated with chemoresistance, LTF, SOD2, STAT1, CDKN2A, CD81, RAC1, and NDRG1 and five factors that may be associated with tumor development, CCN1, DCTN3, MUC1, H1-5, and SLC1A5." (PMID 35421932, 2022). "As with Cal-27 tumor cell lines, each candidate gene caused a significant increase in the proliferation of the candidate gene expressing cell lines compared to the empty vector control cell line (VCP: P = 1.34 × 10−4, DCTN3: P = 1.16 × 10−4, STOML2: P = 2.14 × 10−5)." (PMID 25060540, 2014). "A further two-group analysis between CR and nCR also demonstrated the overexpression of proteins that play a tumor-suppressive role, including AKAP12, DCTN3, and SELENOH, in the CR group." (PMID 36361712, 2022).
infection (1 paper, 2020). The state of being infected such as from the introduction of a foreign agent such as serum, vaccine, antigenic substance or organism. "In addition, the virus recovered rapidly during infection and regained DCTN3 binding, suggesting that the interaction between FMDV 3A and DCTN3 is vital for virus replication in cattle." (PMID 32899635, 2020).
DCTN3 also shares sentences with these, for which no sentence is quoted: cancer (2 papers); Barrett’s esophagus (1).